PLK1 (polo like kinase 1)
Diseases named in the same sentence as PLK1 in open-access papers (continued):
Sharing a sentence is not in itself a finding about the gene and the disease.
lymphoma (19 papers, 2009 to 2025). A malignant (clonal) proliferation of B- lymphocytes or T- lymphocytes which involves the lymph nodes, bone marrow and/or extranodal sites. "We demonstrate that PLK-1 expression is prevalent among these aggressive lymphomas and associated with c-myc expression." (PMID 29383095, 2017). "Because PLK1 has been implicated in molecular cross talk with MYC and volasertib possibly has an inhibitory activity on the BRD4 protein, it is plausible that therapeutic targeting of PLK1 in combination with JQ1 might yield a more favorable therapeutic index in MYC-associated lymphomas." (PMID 30323893, 2018). "In CTCLs, the overexpression of AURKA and the hyperactivation of its downstream target polo-like kinase 1 (PLK1) accelerate mitotic entry of DNA-damaged cells favoring the accumulation of genomic aberrations in this lymphoma." (PMID 33928032, 2021). "In the long term, Plk1(+/−) mice develop tumors with a higher incidence of lymphomas, also accompanied by lung carcinomas, squamous cell carcinomas, and sarcomas." (PMID 30862113, 2019). "The major tumor type is lymphoma, probably due to the rapid proliferation of lymphocytes and the requirement for high expression of Plk1 to maintain the cell proliferation." (PMID 19161615, 2009). "In lymphoma and neuroblastoma cancer cells, Myc downregulation decreases the expression of Plk1." (PMID 30862113, 2019). "FOXM1, Plk-1, and EZH2 are all described as interesting therapeutic targets in both DLBCL and MCL, and high expression of these genes is reported to be associated with poor survival in lymphoma patients." (PMID 31740676, 2019). "Pre-clinical studies suggest that lymphoma cells, particularly those of T-cell origin, may be particularly vulnerable to such agents, and the PLK1 inhibitor MLN0905 has shown in vivo activity in DLBCL xenograft models." (PMID 28416758, 2017). "Additionally, high risk lymphomas rely on AURKA and PLK1 to sustain the high rate of proliferation." (PMID 33928032, 2021). "We also confirmed that PLK1 depletion or inhibition yields the similar effect on EBV lytic reactivation and cell death of EBV-infected lymphoma cells." (PMID 34297745, 2021). "We further demonstrated that PLK1 depletion or inhibition facilitates KSHV reactivation and promotes cell death of KSHV-infected lymphoma cells." (PMID 34297745, 2021). "A year later, a novel formulation based on the SNALP system and targeting polo-like kinase 1 (PLK1) was evaluated in patients with advanced solid tumors and lymphoma that were unaffected by other conservative treatments." (PMID 26056574, 2014). "Evidence that PLK1 are over-expressed in neoplastic cells, including NHL cells, but not in normal cells has stimulated interest in agents such as volasertib in the treatment of lymphoma." (PMID 28416758, 2017). "Double heterozygous mutants [(+/Plk1);(+/rtTA)] treated with Dox since birth displayed a slightly reduced tumor-free survival, accompanied by a slight but non-significant increase in some tumors such as lymphomas and sarcomas." (PMID 30069007, 2018).
squamous cell carcinoma (15 papers, 2004 to 2025). A carcinoma arising from squamous epithelial cells. "Elevated expression of the polo-like kinase 1 (Plk1) correlated to a poor prognosis in epidermoid carcinomas." (PMID 34646387, 2021). "In addition, the expression levels and frequencies of PLK1 were higher in stages 2–4 than those of stage 1 of adenocarcinoma and squamous cell carcinoma, indicating that PLK1 is highly expressed in metastatic NSCLC." (PMID 31548612, 2020). "We investigated the role of PLK1 in the cell response to CPTs in squamous cell carcinoma (SCC) and pediatric sarcoma cell lines and explored the therapeutic potential of the combination of CPT11 and the PLK1 inhibitor BI2536 in CPT-sensitive and -resistant tumor models." (PMID 25826089, 2015). "Because of this, we investigated the correlation between TNFAIP6 and PLK1 expression in LUAD and squamous cell carcinoma (LUSQ)." (PMID 40860188, 2025). "Rigosertib: Squamous cell carcinomas (SCC), one of the most threatening co-pathologies in RDEB, is treated with Rigosertib, a polo-like kinase (PLK)-1 inhibitor leading to apoptosis in cancer cells." (PMID 33076941, 2020). "In agreement with the luciferase assay, accumulation of NOTCH1 protein upon treatment with PLK1 inhibitors was observed in arsenite-untreated and -treated HaCaT cultures as well as in SCC022, a squamous cell carcinoma–derived cell line." (PMID 31597699, 2019). "We have therefore found that only a high gene expression of PLK1 has a pejorative impact on the OS of adenocarcinoma but not squamous cell carcinoma." (PMID 33889306, 2021). "As for pan-cancer analysis, PLK1 exhibited medium expression in cervical adenocarcinoma carcinoma and squamous cell carcinoma tissues, while PLK1 expression was below cutoff value in normal ectocervix and endocervix tissues." (PMID 33354424, 2020).
brain tumor (14 papers, 2012 to 2025). "High PLK1 gene editing efficiency in a brain tumor (up to 38.1%) in orthotopic CSC2-Luc GSC tumor-bearing mice." (PMID 40006568, 2025). "Intravenous administration of iRGD–LHNPs targeting the polo‐like kinase 1 (PLK1) gene plus Lexiscan (to improve brain barrier permeability) inhibited brain tumor proliferation in mice and improved the survival rates of U87 tumor‐bearing mice." (PMID 37166046, 2023). "A significantly higher expression of PLK1 has been observed in brain tumor cells than in corresponding normal brain tissue." (PMID 34680264, 2021). "Our group has demonstrated PLK1 to be a promising therapeutic target for brain tumors as it is highly over-expressed in cancer compared to normal tissue." (PMID 23047041, 2012). "Recently we have shown that PLK1 inhibition delayed tumor growth in an orthotopic brain tumor model and also demonstrated PLK1 to be essential for sustaining the growth of tumorspheres." (PMID 23047041, 2012). "As GBM tumors with higher levels of PLK1 expression have a higher incidence and poorer prognosis, PLK1 could be a promising therapeutic target for brain tumors." (PMID 36091753, 2022). "Following systemic administration, the CRISPR/Cas12a system demonstrated promising brain tumor accumulation that led to extensive EGFR and PLK1 gene editing in both U87MG and patient‐derived GSC xenograft mouse models with negligible off‐target gene editing detected through NGS." (PMID 38943253, 2024). "Unlike other Plks (Plk1,2,3 and 4), the function of Plk5 in cancer development is not yet well understood, but it was recently shown to localize in the nucleus in response to DNA damage and was silenced in brain tumor tissues." (PMID 26908440, 2016).
sarcoma (14 papers, 2015 to 2025). A usually aggressive malignant neoplasm of the soft tissue or bone. "We also knockdown PLK1 and overexpressed the constitutively active PLK1 T210D (TD) in sarcoma cell line U2OS, and found PHGDH increased upon PLK1 KD, while PHGDH decreased upon TD overexpression." (PMID 40475404, 2025). "Activation of 4E-BP1 reduces the levels of the oncogenic proteins ribonucleotide reductase M2 (RRM2) and polo-like kinase 1 (PLK1) in Ewing and other sarcoma cell lines." (PMID 38933441, 2024). "Out of five targets, only knockdown of PLK1 showed significant reduction in cell growth, posing PLK1 as a promising target for a subset of sarcoma patients with high CEP135 expression and poor survival rates." (PMID 36435816, 2022). "Recent work in sarcoma cell lines shows Plk1 inhibition by TAK-960 leads to polyploidy, cell cycle arrest, and apoptosis as methods of tumor suppression." (PMID 29402316, 2018). "The effect of the PLK1 inhibitor TAK‐960 was recently assessed in a panel of sarcoma cell lines, including two MPNST cell lines." (PMID 28556483, 2017). "The association between the two events was further investigated in pediatric sarcoma cell lines as additional tumor models, since a role as survival kinase has been demonstrated for PLK1 in such tumor types." (PMID 25826089, 2015). "Activation of PLK1 and upregulation of the PLK1-mediated signaling pathway in sarcoma patients could, therefore, be due to the high expression of CEP135, an associated upstream PLK1 regulator." (PMID 36435816, 2022). "Overall, these results define a link between ROS and protein synthesis in sarcoma cells and identify a mechanistic connection between ROS and the DNA replication (RRM2) and cell cycle regulatory (PLK1) pathways." (PMID 38933441, 2024). "Indeed, we observed by immunofluorescence that a number of mitotic proteins, such as KIF11, KIF23 and PLK1 were overexpressed in interphase in sarcoma cell lines (data not shown)." (PMID 28035071, 2017). "Here, we assessed the concomitance of an efficient CPT-induced cell death and PLK1 downmodulation in a panel of SCC and pediatric sarcoma cell lines, and confirmed that PLK1 levels were not modulated in cells resistant to CPT-induced apoptosis." (PMID 25826089, 2015).
thyroid cancer (13 papers, 2004 to 2025). "Elevated PLK1 expression has been associated with an increased invasiveness of colorectal, breast, renal, and thyroid cancer cells." (PMID 28953239, 2017). "However, the association between PLK1 and thyroid carcinoma cell invasiveness has yet to be adequately investigated." (PMID 23226764, 2012). "Increased Plk1 expression effectively promotes invasive ability in breast, renal, cervical, and thyroid cancer cells." (PMID 40166466, 2025). "We investigated PLK1 expression in various thyroid neoplasms in order to elucidate its physiological significance in thyroid carcinoma." (PMID 14735186, 2004). "In addition, it has been reported that the downregulation of PLK1 in thyroid cancer cells led to a significant decrease in CD44v6, matrix metalloproteinase (MMP)-2, and MMP-9, which are all key players in tumor invasion and metastasis." (PMID 28953239, 2017). "Polo-like kinase 1 signal was found in a thyroid carcinoma cell line, NPA (lane 18)." (PMID 14735186, 2004). "The present study demonstrated that PLK1 protein expression is upregulated significantly in cancer tissues when compared with cancer-adjacent tissues, and that PLK1 expression correlated with clinical stage and lymphatic metastasis of thyroid carcinoma, as well as with the prognosis of patients." (PMID 23226764, 2012). "Similar results of the CUDC-907-mediated blockage of the S and G2/M phases were shown for pancreatic and thyroid cancers via the downregulation of the cell cycle regulators cyclin B1, AURKA, and PLK1." (PMID 35205815, 2022).
lymph node metastasis (12 papers, 2009 to 2024). "The pooled analysis showed that PLK-1 overexpression was significantly associated with lymph node metastasis, histological grade, clinical stages (p < 0.001 respectively), and tumor grade (p < 0.001)." (PMID 36457496, 2022). "More importantly, GC patients with PLK1 overexpression had inferior survival outcome and a significantly increased risk of lymph node metastasis." (PMID 29190933, 2017). "The increased expression of PLK1 was positively associated with lymph node metastasis (OR: 1.78, 95% CI: 1.13–2.80, P=0.013, random effect model) and advanced TNM stage (OR: 1.48, 95% CI: 1.02–2.15, P=0.038, random effect model)." (PMID 29190933, 2017). "Furthermore, a large meta-analysis including 11 studies (1147 CRC patients) also found a statistically significant association between PLK1 over-expression and adverse clinico-pathological characteristics, such as advanced stage and lymph node metastasis, further corroborating our findings." (PMID 39451218, 2024). "This study demonstrated that the dysregulated activation of PLK1 signaling serves as a predictive prognostic biomarker for lymph node metastasis." (PMID 39451218, 2024). "In head and neck cancer, PLK-1 levels positively correlate with lymph node metastasis and poor prognosis, thus implicating PLK-1 as a prognostic marker." (PMID 38540116, 2024). "Intriguingly, multivariate logistic regression analysis identified PLK1 as an independent predictor of lymph node metastasis." (PMID 39451218, 2024). "Furthermore, the results revealed that high PLK1 levels were significantly associated with larger tumor size (OR=1.703, 95%CIs: 1.315-2.205, P<0.001), higher pathological grading (OR=6.028, 95%CIs: 2.639-13.772, P<0.001), and lymph node metastasis (OR= 1.524, 95%CIs: 1.192-1.950, P=0.001)." (PMID 28915707, 2017). "The expression of PLK1 correlated with clinical stage, lymph node metastasis and prognosis of anaplastic thyroid." (PMID 23226764, 2012). "Interestingly, on multivariate logistic regression analysis, we found that PLK1 was an independent predictor of lymph node metastasis (Odds ratio = 1.61, 95% Confidence interval = 1.20–2.17, p = 0.0016)." (PMID 39451218, 2024). "Importantly, multivariate analysis revealed that PLK1 serves as an independent predictor of lymph node metastasis, underscoring its potential role in CRC recurrence and metastasis." (PMID 39451218, 2024). "Moreover, we conducted univariate analysis and identified five prognostic parameters: clinical stage, tumor size, lymph node metastasis, distant metastasis, and PLK1 protein expression." (PMID 28724602, 2017). "Additionally, this meta-analysis documented that elevated PLK1 was closely linked with advanced TNM stage and lymph node metastasis." (PMID 29190933, 2017). "Thus, we sequentially explored that clinical significance of PLK1 in lung squamous cell carcinoma patients, and found high expression of PLK1 protein was correlated with differentiated degree, clinical stage, tumor size, lymph node metastasis, and distant metastasis." (PMID 28724602, 2017).
rhabdomyosarcoma (12 papers, 2010 to 2025). A rare aggressive malignant mesenchymal neoplasm arising from skeletal muscle. "High PLK1 expression has been associated with poor prognosis in several cancers, including rhabdomyosarcoma." (PMID 37958442, 2023). "Summary of rhabdomyosarcoma (RMS) preclinical studies for PLK1 inhibitors combined with other drugs." (PMID 31824851, 2019). "Overexpression of PLK1 is observed in several human tumors, including prostate and ovarian cancers, and muscle cell-derived rhabdomyosarcoma." (PMID 31393265, 2019). "This is supported in rhabdomyosarcoma models by characterization of molecular and phenotypic effects of reducing and inhibiting PLK1, including changes to the PAX3-FOXO1 fusion protein." (PMID 31824851, 2019). "Recently, PLK1 was reported to phosphorylate PAX3-FOXO1 in alveolar rhabdomyosarcoma, and inhibition triggered tumor regressions." (PMID 26380223, 2015). "Further development of novel therapeutic strategies including PLK1 inhibition may ultimately benefit young patients with rhabdomyosarcoma and other cancers." (PMID 31824851, 2019). "RNA interference and small molecule inhibitor screens suggest that Plk1 may be a relevant therapeutic target in a variety of pediatric malignancies including neuroblastoma, rhabdomyosarcoma, and OS." (PMID 26380223, 2015). "Previous studies suggested that PLK1 inhibition by Volasertib promotes the degradation of PAX3-FOXO1, a fusion protein frequently found in rhabdomyosarcoma patients, thereby inhibiting cancer growth in PDX models." (PMID 38177929, 2024). "Moreover, preclinical studies using the combination of PLK1 inhibitors, such as volasertib, along with other agents, such as etoposide, vincristine, vinblastine, vinorelbine, or eribulin, is widely beneficial in treating young patients with rhabdomyosarcoma and other cancers." (PMID 37958442, 2023).
head and neck cancer (11 papers, 2017 to 2025). A primary or metastatic malignant neoplasm affecting the head and neck. "Further, they are consistent with synergistic effects between Aurora A, the upstream kinase activating Plk1, and Wee1 inhibition in head and neck cancer models." (PMID 40256327, 2025). "The IC50 value of volasertib observed in this study falls in the range seen in other reports evaluating PLK-1 inhibition in head and neck cancer cells." (PMID 38540116, 2024). "We used this database to assess the dependence of a large panel of head and neck cancer cell lines on the expression of PLK1, AURKA, TPR, NUF2, NDC80, and TTK." (PMID 39392349, 2024). "Analysis of single-cell transcriptomic data also confirmed that PLK1 expression was positively correlated with SKA3 levels in head and neck cancer (GEO accession number: GSE103322)." (PMID 33106477, 2020). "In head and neck cancer, the effects of PLK-1 mRNA depletion is enhanced with the addition of radiotherapy, indicating that depleting PLK-1 may enhance the cytotoxic effects of radiotherapy." (PMID 38540116, 2024).
nasopharyngeal carcinoma (11 papers, 2012 to 2025). A carcinoma arising from the nasopharyngeal epithelium. "We found that PLK1 is overexpressed in cells from nasopharyngeal carcinoma, a highly invasive cancer with poor prognosis, in comparison to normal nasopharyngeal epithelial cells." (PMID 25871386, 2015). "MiR-100-5p targets Plk1 (polo-like kinase 1), a critical regulator of many stages of mitosis, resulting in the inhibition of cancer progression in nasopharyngeal cancer cell lines." (PMID 24223210, 2013). "Indeed, nasopharyngeal carcinoma and diffuse midline glioma cells have shown increased sensitivity to co-inhibition of PLK1 and AURKA compared to BI-2536 or AURKA inhibitors as a single agent." (PMID 39085197, 2024). "The experimental results showed that polo-like kinase 1 (PLK1) siRNA transfection mediated by FA-PEG5000-DSPE could selectively inhibit the growth of human nasopharyngeal carcinoma KB cells." (PMID 36678807, 2023). "In a previous study, PLK1 has been reported to be a miR-100 target in human nasopharyngeal cancer." (PMID 22246341, 2012). "Indeed, pharmacological inhibition of PLK1 and AURKA demonstrated superior antitumor activity compared with either single drug treatment in nasopharyngeal carcinoma and was minimally harmful to normal epithelial cells." (PMID 39085197, 2024).
non-Hodgkin lymphoma (11 papers, 2010 to 2023). Distinct from Hodgkin lymphoma both morphologically and biologically, non-Hodgkin lymphoma (NHL) is characterized by the absence of Reed-Sternberg cells, can occur at any age, and usually presents as a localized or generalized lymphadenopathy associated with fever and weight loss. "The observation that PLK1 is overexpressed in tumor cells, including non-Hodgkin's lymphoma, where it is associated with a poor prognosis, but not in normal cells, makes it a logical target for therapeutic intervention." (PMID 28416758, 2017). "GSK461364 is an ATP-competitive inhibitor of polo-like kinase 1 (Plk1) that currently has only one completed phase I clinical trial for non-Hodgkin’s lymphoma." (PMID 36286305, 2022).